CD6 (CD6 molecule)
Diseases named in the same sentence as CD6 in open-access papers (continued):
Sharing a sentence is not in itself a finding about the gene and the disease.
autoimmune disease (continued). "Starting at 9 to 10 weeks of age (close to the time when autoimmune disease is detected) and continuing up until 29 weeks of age (when systemic autoimmune disease is well-established), MRL/lpr mice were treated with anti-CD6, isotype control, cyclophosphamide, or mycophenolate mofetil (MMF)." (PMID 34981775, 2022). "It has been demonstrated that inhibiting CD6 using an anti-CD6 mAb (UMCD6) significantly increases the ability of human lymphocytes to destroy cancer cells without having negative effects on autoimmune diseases." (PMID 35111194, 2021). "Interestingly, soluble CD6 and CD5 have been detected in normal human sera, and their levels found to be increased in autoimmune diseases, thus suggesting a feedback loop to reduce direct lymphocyte activation by pathogens." (PMID 22076177, 2010). "Mice lacking CD6 are less prone than their WT counterpart to develop experimental autoimmune encephalomyelitis and T cell–mediated autoimmune retinal destruction, suggesting that CD6 has a net costimulatory effect in the development of several autoimmune diseases." (PMID 33125054, 2021).
multiple sclerosis (24 papers, 2011 to 2025). A progressive autoimmune disorder affecting the central nervous system resulting in demyelination. "CD6 was first identified and validated as risk gene for multiple sclerosis (MS) in 2009 and, soon after, the CD6-ALCAM axis was shown to play a crucial role in the pathogenesis of this disease." (PMID 36275816, 2022). "In recent studies, CD6 has been identified as a susceptibility gene in both multiple sclerosis and RA." (PMID 29190740, 2017). "This comes at a time of growing expectation that seems to place CD6 as a global therapeutic target for immune-mediated inflammatory diseases, in line with multiple sclerosis high risk CD6 gene variants." (PMID 29033937, 2017). "The recent marketing of a humanized anti-CD6 mAb (itolizumab), together with the identification of CD6 gene as a multiple sclerosis susceptibility locus, has renewed the interest in the study of this relatively neglected lymphocyte receptor." (PMID 28611770, 2017). "This contrasts with the identification of CD6 as a significant susceptibility locus for multiple sclerosis in genome-wide association studies and the promising results of treating some autoimmune disorders with non-depleting anti-CD6 mAb." (PMID 28713387, 2017). "The dual effects of CD6 make it difficult to interpret the consequences of SNPs that alter the expression of CD6 and correlate with susceptibility to multiple sclerosis." (PMID 26146185, 2015). "In particular, people with multiple sclerosis on natalizumab had lower CD6, CDCP1, CXCL13, CXCL9, NfL, TNFRSF10a, TNFSF13B and VCAN (P < 0.036)." (PMID 37361716, 2023). "We recently showed CD6 to be essential in murine models of multiple sclerosis (MS), uveitis, and rheumatoid arthritis (RA)." (PMID 33497367, 2021). "In both CD6–/– mice and in CD6-humanized mice treated with anti-CD6, robust protective effects were seen in mouse models of multiple sclerosis, autoimmune uveitis, and RA." (PMID 33497367, 2021). "Importantly, CD6 has recently reclaimed attention as a focus of research: the CD6 gene, together with the gene for its ligand ALCAM, was identified as a susceptibility locus and a potential target for treatment of multiple sclerosis." (PMID 30356797, 2018). "In autoimmune conditions such as multiple sclerosis, while one study showed lower expression of CD6 mRNA in patients than in healthy individuals, a recent report suggests higher CD6 expression in peripheral blood T-cells as well as cerebrospinal fluid (CSF) T-cells in patients with active lesions." (PMID 28672038, 2017). "CUB domain-containing protein 1 is a ligand for CD6, which is a type I transmembrane glycoprotein expressed by T-lymphocytes and has been described to be involved in the pathophysiology of autoimmune-mediated diseases as multiple sclerosis and rheumatoid arthritis." (PMID 41154673, 2025). "We have developed CD6-knockout mice and CD6-humanized mice and showed the genetic depletion of CD6, or pharmaceutic blockage of CD6 using mAbs, protects the mice from models of T cell–mediated diseases such as multiple sclerosis, rheumatoid arthritis, and autoimmune uveitis." (PMID 37917882, 2023). "Importantly, altered allelic expression of two imprinted genes (ZNF331 and GNAS) and five non-imprinted genes (ABLIM1, UBE2I, KIAA1267, CD6, and ATHL1) were detected between the multiple sclerosis discordant co-twins." (PMID 31850058, 2019).
Autoimmunity (21 papers, 2010 to 2025). The occurrence of an immune reaction against the organism's own cells or tissues. "In contrast to its role in autoimmunity, but consistent with its function in the presence of superantigens, we found that CD6 deficiency enhances CD4 T cell activation and CD4 T cell help to germinal center-dependent antiviral humoral responses." (PMID 39679790, 2025). "CDCP1 is a widely expressed transmembrane glycoprotein that acts as a ligand for T cell-expressed Cluster of Differentiation 6 (CD6),and is implicated in autoimmune conditions." (PMID 38762535, 2024). "As such, evolutionarily selected and/or functionally relevant polymorphisms in the CD5 and CD6 loci have been shown to impact a wide variety of immune-related disorders such as autoimmunity and cancer, often considered two sides of the same coin." (PMID 34070159, 2021). "Importantly, the ALCAM/CD6 co-stimulatory pathway has been implicated in collagen-induced arthritis and other models of autoimmunity, and phase 1 clinical trials with anti-CD6 monoclonal antibody therapy in RA patients produced encouraging results." (PMID 37691918, 2023). "Splenomegaly at the end of the experimental period (week 5)—a hallmark of the cGvHD-induced autoimmunity model—was lower in CD6−/− mice and explained by lower in vivo proliferation (low BrdU incorporation in the absence of vis-à-vis differences in apoptotic cell levels)." (PMID 28611770, 2017). "This “dual” behaviour of CD6 as a rheostat-type signalosome highlights its potential as a target for developing therapeutic strategies in cancer, infectious diseases, and autoimmunity." (PMID 40642095, 2025). "This dual role should be taken into consideration while translating experimental data in to clinical applications, particularly in the development of CD6-targeted therapies for autoimmune disorders and cancer." (PMID 40642095, 2025). "The interaction between CD6/CD166 is being studied for its clinical applications in both autoimmunity and cancer." (PMID 39840036, 2024). "CD6 is a target protein for regulating immune responses and is required for the development of several mouse models of autoimmunity." (PMID 37886483, 2023). "CD6 is a surface membrane antigen of T-lymphocytes involved in the activation of T cells, and considered a promising target for autoimmunity and neuroinflammation." (PMID 35422091, 2022). "Knockout mice of CD6 and its ligands have been extensively studied in models of inflammation and autoimmunity." (PMID 36275816, 2022). "Furthermore, in preclinical murine models of autoimmunity, inhibition of CD6 signaling was shown to prevent TCR co-stimulation, thereby limiting activation of autoreactive T cells." (PMID 39679790, 2025). "CD6 is currently considered as a potential immunotherapeutic target in autoimmunity and cancer." (PMID 40642095, 2025). "In autoimmunity, CD166 has been implicated in the pathogenesis of lupus nephritis, rheumatoid arthritis, Sjogren’s syndrome, and inflammatory bowel disease in which both CD6 and CD166 are overexpressed." (PMID 39840036, 2024). "CD6 signaling can therefore modulate the production of cytokines and other immune mediators, ensuring a balanced immune response that prevents excessive inflammation and autoimmunity." (PMID 39840036, 2024). "This dual role of CD5 and CD6 as both immunomodulatory and microbial PRR receptors is supported by pre-clinical models of infection, autoimmunity and cancer involving Cd5- and Cd6-deficient mouse lines, as well as infusion of wild-type mice with soluble CD5 and CD6 proteins." (PMID 36211446, 2022). "Accordingly, the authors claim that additional studies will be required to unravel the reasons underlying the apparent differences between different autoimmune models and genetically different mouse strains in the etiopathogenic role of CD6 in autoimmunity development." (PMID 29033937, 2017).
Autoimmunity (continued). "Moreover, the strong expression of CD6 ligands on cancer cells suggests that lymphocyte-engaging therapies such as anti-CD6 should be advanced into clinical trials based on the findings that CD6 blockade concurrently reduces T-cell autoimmunity and increases T-cell and NK-cell cytotoxicity." (PMID 39996744, 2025). "Here, we review available information on CD5 and CD6 as targets of natural selection as well as on the role of CD5 and CD6 variation in autoimmunity and cancer." (PMID 34070159, 2021). "Evidence from genetically-modified mouse models indicates that the absence or blockade of CD5- and CD6-mediated signals results in dysregulated immune responses, which may be deleterious or advantageous in some pathological conditions, such as infection, cancer or autoimmunity." (PMID 33287301, 2020). "Indeed, the humanized anti-CD6 SRCR-D1 clone T1h which does not interfere with the CD6-ALCAM interactions may have therapeutic implications in oncology, transplantation, and autoimmunity." (PMID 22076177, 2010).
rheumatoid arthritis (15 papers, 2010 to 2025). A chronic, systemic autoimmune disorder characterized by inflammation in the synovial membranes and articular surfaces. "Genetically, single nucleotide polymorphisms of CD6 have been reported in the evolution of multiple autoimmune diseases, such as MS, rheumatoid arthritis and Behcet’s disease." (PMID 36159854, 2022). "The proportion of CD6-positive cells in B cells is decreased in patients with primary SS compared to those with rheumatoid arthritis." (PMID 39996744, 2025). "Recent approaches to CD6 targeting therapies include itolizumab, a humanized anti-CD6 mAb in psoriasic patients, in view to extend its use to rheumatoid arthritis and Sjögren’s syndrome." (PMID 28611770, 2017). "In four cases, our top SNV had been associated with an inflammatory disease in previous GWAS: rs113010081/CCL4 with inflammatory bowel disease, rs1569723/CD40 with Crohn’s disease, rs4239702/CD40 with rheumatoid arthritis and rs11230563/CD6 with ulcerative colitis." (PMID 31727947, 2019). "Similar to rheumatoid arthritis, autoimmune uveitis (EAU) is another chronic autoimmune disease in which CD6 is believed to be involved in its pathogenesis." (PMID 39996744, 2025).
inflammatory bowel disease (12 papers, 2008 to 2025). A spectrum of small and large bowel inflammatory diseases of unknown etiology. "Using two-sample MR, we showed that CD6 levels were causally associated with inflammatory bowel disease (IBD) (beta 0.20, se 0.04, P 2.59 × 10−6)." (PMID 32641083, 2020). "Recent research also indicates that CD6 is a novel risk gene for inflammatory bowel disease (IBD)." (PMID 39595128, 2024). "We demonstrated putative causal relationships between CD6 and IL18R1 with inflammatory bowel disease and between IL12B and Crohn’s disease." (PMID 32641083, 2020). "In the mediation analysis, we identified two circulating inflammatory proteins (CD6, CCL4) playing a mediating role between lipidome and inflammatory bowel disease." (PMID 40937162, 2025). "Our MR study provides genetic evidence supporting the role of several inflammatory cytokines (CD6, CCL4) in mediating the impact of lipidome on inflammatory bowel diseases." (PMID 40937162, 2025). "Similarly, the expression of both CD6 and ALCAM (CD166) is markedly increased in the inflamed mucosa of inflammatory bowel disease patients compared with normal controls." (PMID 36275816, 2022).
COVID-19 (8 papers, 2020 to 2024). A disease caused by infection with severe acute respiratory syndrome coronavirus 2. "ILC1 cells from COVID-19 patients upregulated expression of CD6 (adj.p= 2.3e-06), which encodes a cell surface protein that has been shown to costimulate T cell activation and proliferation." (PMID 39026668, 2024). "Thus, a downregulated CD6 at baseline is probably associated with overactivation of T cell response among severe COVID-19 patients." (PMID 35350784, 2022). "Proteins that were decreased in abundance in fatal COVID-19 included the epithelial damage-associated molecular pattern IL-33, IL-1 receptor-associated kinase-1 (IRAK1), and the lymphocyte receptors CD5 and CD6." (PMID 34710339, 2022). "Here, we report the use of a well-known anti-inflammatory antibody targeting CD6 to treat the CRS arising in COVID-19 patients." (PMID 33397150, 2021). "However, CD6 was found to be lower in female COVID-19 patients." (PMID 37832397, 2023).
lupus nephritis (8 papers, 2022 to 2025). Glomerulonephritis in the context of systemic lupus erythematosus. "It is a ligand of CD6, and the CD6/ALCAM pathway promotes lupus nephritis via T-cell-mediated responses." (PMID 40375995, 2025). "T cells are central to the pathogenesis of lupus nephritis (LN), and blockade of CD6 in a model of spontaneous lupus and immune-complex glomerulonephritis resulted in significant decreases in immune cells, inflammatory markers, and disease markers." (PMID 38570749, 2024). "CD6 expression was established in renal-infiltrating T cells that contribute to the pathology of lupus nephritis, while high ALCAM expression was established in structural renal cells that are subject to damage during LN disease." (PMID 34981775, 2022). "To specifically examine the contribution of CD6 to lupus nephritis, we utilized the mouse model of nephrotoxic serum nephritis (NTN)." (PMID 34981775, 2022). "CD6 was identified as a therapeutic target of lupus nephritis." (PMID 40171199, 2025). "Itolizumab and CD6 CAR-T cells are currently being evaluated in multiple clinical trials in patients with severe diseases, including GVHD, lupus nephritis, and uncontrolled asthma." (PMID 39996744, 2025). "The same axis of CD6-ALCAM was reported to be involved in SLE disease, especially in patients with lupus nephritis." (PMID 39026665, 2024).
Sepsis (8 papers, 2017 to 2025). Sepsis is defined as life-threatening organ dysfunction caused by a dysregulated host response to infection. "In this study, we found that the CD6‐ALCAM pathway was abnormally activated in sepsis, which may be linked to the reduction in T‐lymphocyte subsets during disease." (PMID 39578684, 2024). "T-cell surface glycoprotein CD6 isoform levels (CD6) (OR = 0.858, 95% CI = 0.737 ~ 0.999, P = 0.049) and Cystatin D levels (OR = 0.808, 95% CI = 0.695 ~ 0.940, P = 0.006) were associated with a decreased risk of sepsis (28-day mortality)." (PMID 39176264, 2024). "Catala and colleagues have discovered that triggering monobacterial and polymicrobial sepsis in CD6 (−/−) mice leads to reduced survival probabilities, along with heightened levels of bacterial counts and pro‐inflammatory cytokines." (PMID 40453734, 2025). "Their studies also showed that the adoptive transfer of wild-type cells and serum to CD6−/− mice improves their survival after sepsis, highlighting CD6’s important role in early responses to bacterial infections." (PMID 39996744, 2025). "Further research is needed to clarify the specific mechanisms involved, but the CD6‐ALCAM pathway holds potential as a therapeutic target for sepsis." (PMID 39578684, 2024). "As Lozano and colleagues convincingly described, CD6 protects mice from LPS-induced septic shock and from polymicrobial sepsis." (PMID 28878773, 2017). "Finally, based on these analyses, the CD6‐ALCAM pathway was selected for further investigation due to its abnormal interaction strength in sepsis." (PMID 39578684, 2024). "By and Large, increasing account of CD28+ DN Treg cells may increase the levels of the T-cell surface glycoprotein CD6 isoform and enhance the efficiency of Tregs to repress immune responses, aggravating sepsis." (PMID 39076981, 2024). "CD6 is able to impact on the efficiency of Tregs, and when CD6 expression is increased directly or indirectly, Tregs are more able to repress immune responses, which may aggravate sepsis." (PMID 39076981, 2024). "Notably, pathways such as CD6‐ALCAM were more activated in sepsis, potentially due to T cell suppression." (PMID 39578684, 2024). "In conclusion, the present findings that short (11-mer) peptide sequences can retain the bacterial-binding properties of the whole extracellular region of CD6 open cost-effective opportunities for developing new adjunctive alternatives to currently available sepsis treatment." (PMID 29706953, 2018). "However, it should be noted that for CD6 to have a biological protective function, there needs to be no proportional correlation of the binding strength to pathogens namely when the model addressing the protective effect of CD6 is sepsis." (PMID 28878773, 2017). "The CD6‐ALCAM pathway was more activated in sepsis than in healthy individuals, suggesting that this pathway may play a crucial role in the mechanisms underlying sepsis." (PMID 39578684, 2024). "Among these, the CD6‐ALCAM pathway, which was abnormally activated in sepsis, was selected for in‐depth analysis." (PMID 39578684, 2024). "The CD6.PD3 peptide possesses broad bacterial-agglutination properties and improved survival of mice undergoing polymicrobial sepsis in a dose- and time-dependent manner." (PMID 29706953, 2018). "The CD6‐ALCAM pathway may influence the inflammatory response and immunosuppression by promoting T cell proliferation in sepsis." (PMID 39578684, 2024). "Another remarkable finding is CD6.PD3 peptide’s additive/synergistic effect on mice survival when coadministered with Imipenem/Cilastatin, a member of the carbapenem family considered as first-choice treatment in critical care patients undergoing sepsis." (PMID 29706953, 2018). "In the context of sepsis leading to 28-day mortality, our analysis showed that the relative count of CD28+ DN Treg cells within the T-cell population could increase the levels of the T-cell surface glycoprotein CD6 isoform." (PMID 39076981, 2024).
Sepsis (continued). "CD6.PD1 and CD6.PD2 high affinity (and also CD6.PD3) to LPS and LTA makes these peptides suitable candidates for new supportive non-antibiotic strategies against sepsis." (PMID 29706953, 2018).
breast carcinoma (7 papers, 2011 to 2025). "For instance, B3GNT7 and CTSV predicted detrimental prognosis in BRCA2-mut breast cancers, and CD6, CXCL9, and CXCL13 predicted favorable outcomes in BRCA1-mut ovarian cancers." (PMID 40647506, 2025). "Using this strict approach, we selected two genes associated with a detrimental prognosis: B3GNT7 and CTSV in BRCA2-mut breast cancers, and three with a favorable prognosis: CD6, CXCL9, and CXCL13 in BRCA1-mut ovarian cancers." (PMID 40647506, 2025). "In the same study, it was shown that the blocking of CD6 in vivo resulted in the rapid rejection of breast cancer xenografts." (PMID 36291815, 2022). "In addition, the data provide the first evidence of a negative correlation between CD318 expression levels and CD6+ lymphocyte infiltration in breast cancer tissue samples." (PMID 40391211, 2025).